EGFL7 (EGF like domain multiple 7)
Diseases named in the same sentence as EGFL7 in open-access papers (continued):
Sharing a sentence is not in itself a finding about the gene and the disease.
tumor (continued). "Following the initial observation that EGFL7-overexpressing tumor cells showed enhanced tumor growth and metastasis in immunocompetent but not in immunodeficient mice with an impaired influx of inflammatory cells, it was shown that EGFL7 modulates the immune cell recruitment process." (PMID 33804387, 2021). "Thus, EGFL6 and EGFL7 had a similar performance in tumor immunity and micro-environment." (PMID 33391349, 2020). "Put together, these findings reflect that EGFL7 may be critical for tumor growth and metastasis." (PMID 29363485, 2018). "Moreover, miR-126 could reduce cell proliferation and tumor angiogenesis of HCC via decreasing EGFL7 expression, which is similar to our results, but the negative regulation of miR-126 on ERK signaling pathway was not involved." (PMID 28881749, 2017). "This corresponds rather well with basic angiogenic knowledge stating that tumor associated ECs are highly activated, leaky, and release high levels of pro-angiogenic proteins such as EGFL72 as compared to the remaining vascular network, where EGFL7 expression is rather limited in the quiescent ECs5." (PMID 28539619, 2017). "Therefore, the miR-126 overexpression and inhibition of EGFL7 expression might suppress the proliferation ability of tumor cells in vivo." (PMID 28881749, 2017). "Compared with the blank and miR-126 inhibitors + si-EGFL7 groups, significant increases in tumor sizes were observed in the miR-126 inhibitors group at the first 10 days after transfection (both P < 0.05), while the tumor size was decreased in the miR-126 mimics and si-EGFL7 groups (all P < 0.05)." (PMID 27611944, 2016). "In contrast, tumor promoters such as MYBL2, TYMS, MYC, MCM7, and EGFL7 were downregulated in EF-24–treated cells." (PMID 40986633, 2025). "miR-126, contrary to miR-21 and miR-221, can act as a tumour suppressor in several carcinomas such as lung, gastric, breast and PDAC through the inhibition of epidermal growth-factor-like domain 7 (EGFL7), Crk, and SLC7A5." (PMID 33573274, 2021). "In this review, we introduce the angiocrine factor EGFL7 and one of its receptors (ITGB3) as regulators of angiogenesis and summarize recent knowledge on their involvement in tumor metastasis." (PMID 33804387, 2021). "EGFL7 alters cellular adhesion to the ECM and migratory behavior of tumor and immune cells contributing to tumor metastasis." (PMID 33804387, 2021). "On the basis of the ESTIMATE algorithm, EGLF6, EGFL7, and EGFL8 were also related to the different degrees of tumor-stromal cell and immune cell infiltrates." (PMID 33391349, 2020). "In recent years, several studies have shown that EGFL6, EGFL7, and EGFL8 play a crucial role in the process of tumor growth, invasion, and distant metastasis." (PMID 33391349, 2020). "Due to the similarities between mesothelial lineage tumor and GCT, we try to illuminate the role of miR-126 and EGFL7 in GCT." (PMID 31245291, 2019). "Furthermore, using the Transwell system, the adhesion, migration, and angiogenesis of HUVEC were down regulated after EGFL7 knockdown in U2OS, which suggests that EGFL7 may influence tumor growth and metastasis by affecting the angiogenesis of endothelial cells." (PMID 29363485, 2018). "CD31 was significantly lower in the groups treated with anti‐EGFL7, anti‐VEGF, or a combination of both blocking antibodies as compared to control, advocating treatment‐driven inhibition of tumor vascularization." (PMID 30065025, 2018). "In order to understand the molecular mechanisms behind EGFL7's action, we focused on its role within the ECM, a key component of tumor angiogenesis." (PMID 30065025, 2018). "Upon tumor engraftment, mice were treated with isotype control, anti‐VEGF, or a combination of anti‐VEGF plus anti‐EGFL7 antibodies together with TMD." (PMID 30065025, 2018).
tumor (continued). "The company has developed monoclonal antibodies against EGFL7 which have been shown to augment the efficacy of anti-VEGF therapies in pruning and damaging tumor vessels in a model of non-small cell lung cancer." (PMID 25705891, 2015). "A positive significant correlation was demonstrated between the VA estimates of EGFL7 and miRNA-126 in stage III and IV tumours." (PMID 25592646, 2015). "Recently miR-126 has been reported to be a tumour suppressor in various cancer types including RCC regulating target genes like CRK, VEGF and EGFL7 in cancer cells." (PMID 24428907, 2014). "Additionally, considering the dual effects of EGFL7 on endothelium and the tumor parenchyma, the development of novel agents targeting EGFL7 and its homolog EGFL8 may prove to be valuable additions to the already existing array of therapeutic strategies against cancer." (PMID 20529320, 2010). "A recent study by our team has identified serum Egfl7 level as a valuable marker for the diagnosis of early HCC, suggesting HCC cells can secrete Egfl7 and may play a certain role in HCC tumour microenvironment." (PMID 37480091, 2023). "However, it was found that MFAP2 is necessary for depositing EGFL7 into microfibrils, which is crucial for vascular development, showing that MFAP2 is important in tumor angiogenesis." (PMID 36530974, 2022). "Indeed, EGFL7 binds to all members of the LOX family including LOX and LOXL1–4, indicating its importance in the regulation of tumor ECM stiffness." (PMID 33804387, 2021). "In addition, EGFL6, EGFL7, and EGFL8 were found to be related to immune subtypes and tumor microenvironment." (PMID 33391349, 2020). "High expression levels of EGFL7 have been previously reported in certain solid tumors; however, the protein was found to be secreted by ECs rather than tumor cells." (PMID 32117731, 2020). "Epidermal growth factor-like domain multiple 7 (EGFL7), which modulates Notch2/DLL3 signaling, is involved in regulation of GHoma proliferation and invasiveness, and has been correlated with poor prognosis and tumor grade." (PMID 31508369, 2019). "It appears that the initial tumor burden seems to influence the steady state levels of cir-EGFL7, i.e. primary tumor resected or not." (PMID 28539619, 2017). "Thus, in the present study, we studied the effects of miR-126 on tumor proliferation and angiogenesis of HCC by targeting EGFL7." (PMID 27611944, 2016). "In conclusion, miR-126 could inhibit tumor proliferation and angiogenesis of HCC by down-regulating EGFL7 expression." (PMID 27611944, 2016). "The aim of this descriptive study was to analyse the expression of EGFL7 and miRNA-126 in the primary tumours of stage II-IV CRC and whether this expression changed in paired samples of primary tumours, regional lymph node metastases and distant metastases." (PMID 25592646, 2015). "Similarly, miR-338-3p also does not target Nfat5; instead, it targets EGF-like domain 7 (EGFL7), a gene potentially promoting tumour cell growth." (PMID 34064510, 2021). "Therefore, EGLF6, EGFL7, and EGFL8 had a significantly negative association with tumor stem cell-like features measured by DNAs and RNAs; however, their negative correlation in RNAs was not prominent and only manifested in individual tumors." (PMID 33391349, 2020). "Furthermore, miR-126 could inhibit tumor proliferation and angiogenesis of HCC by down-regulating EGFL7 expression." (PMID 27611944, 2016). "The surface of tumors from low EGFL7-expressing GC cells exhibited ischemic necrosis, suggesting that EGFL7 knockdown may reduce tumor size not by reducing proliferation but by suppressing angiogenesis." (PMID 24945379, 2014). "Finally, although obvious differences in survival can be noted among tumor stages (stages 1, 2, 3 or 4), the comparison of the curves (low EGFL7 expression vs. high EGFL7 expression) within each stage (stages 1, 2, 3 or 4) was not statistically different (P > 0.05)." (PMID 37957249, 2023).
tumor (continued). "Although anti-EGFL7 therapy alone could not sufficiently control tumor growth, the current state of research indicates that combining anti-EGFL7 therapy with other anti-cancer strategies such as chemotherapy might improve the efficacy of conventional anti-cancer strategies." (PMID 33804387, 2021). "In this study, the proliferation and apoptosis of both cell types exhibited no variation after EGFL7 shRNA interference with U2OS and HUVEC, which indicates that EGFL7 may not affect cell proliferation, and there may be other EGFL7 mechanisms affecting tumor growth." (PMID 29363485, 2018). "Recent studies have suggested a relationship between efficacy of first line treatment and tumor expression of EGFL711, 12, but the role of circulating EGFL7 (cir-EGFL7) in this context has so far not been explored." (PMID 28539619, 2017). "Conversely, the average MVD was higher in tumors from EGFL7-overexpressing MKN28-EGFL7 cells, suggesting that EGFL7 promotes tumor growth through angiogenesis rather than direct effects on proliferation." (PMID 24945379, 2014). "In addition, large differences were observed in the expression levels of EGFL6, EGFL7, and EGFL8 among different tumor types and compared with normal tissues (P < 0.05)." (PMID 33391349, 2020). "Tumor expression levels of miR-126 did not significantly differ between LC-COPD and LC patients, whereas in the former patients, an almost significant decrease in EGFL-7 expression was observed (p = 0.073), together with a decrease in TOM-1 and CRK expression and a rise in angiopoietin-2 content." (PMID 29371906, 2018).
cancer (48 papers, 2009 to 2025). A tumor composed of atypical neoplastic, often pleomorphic cells that invade other tissues. "Epidermal growth factor-like domain-containing protein 7 (EGFL7), also known as vascular endothelial statin, is encoded by the EGFL7 gene and involved in regulating the formation of vascular ducts and the progression of many cancers." (PMID 35155211, 2021). "The univariate Cox proportional hazard regression model showed that EGFL6 and EGFL7 were the risk factors to predict poor prognosis of cancers." (PMID 33391349, 2020). "EPIDERMAL GROWTH FACTOR-LIKE DOMAIN 7 (EGFL7) is also associated with cancer development, and the methylation signal detected in EGFL7 covers most of the gene-body." (PMID 31717838, 2019). "Moreover, Egfl7, also known as VE-statin, promotes cancer suppression by inhibiting TIL-associated endothelial molecules." (PMID 35774776, 2022). "Furthermore, we found that the AKT signaling pathway was associated with miR-126 and EGFL7 in cancer GCs." (PMID 31245291, 2019). "Since the transcription of miRNAs with anti-oncogenic activity is often regulated by TFs that are themselves oncosuppressors, we focused on EBF1, ETS2, and KLF2, which are frequently deregulated in cancer, and can bind to the EGFL7/miR-126 promoter regions." (PMID 39796183, 2025). "We focused on KLF2 (Krüppel-Like Factor 2), ETS2 (ETS Proto-Oncogene 2), and EBF1 (Early B Cell Factor 1), which are usually deregulated in several cancers, including BC, and have several putative binding sites on the EGFL7 gene." (PMID 39796183, 2025). "It has been noted that Egfl7 plays a role in vascular repair, CNS inflammation, and cancer angiogenesis." (PMID 39013903, 2024). "EGFL7 also plays a role in vascular repair, CNS inflammation, tumor metastasis, and cancer angiogenesis." (PMID 39013903, 2024). "The presence of EGFL7 mRNA transcripts found in microdissected cancer cells indicates the endogenic activation of the EGFL7 gene in human HGOSCs." (PMID 35630004, 2022). "In detail, activation of EGFL7 was detected in cancer epithelium (9/59, 15.25%), endothelium (8/59, 13.56%), or in both: cancer epithelium and adjacent endothelium (4/59, 6.78%)." (PMID 35630004, 2022). "Considering that heterogeneity plays a key role in cancer management, we also performed the EGFL7 expression assay at single cells’ level using the human protein atlas data base." (PMID 35494025, 2022). "Further, ICAM-1 was also found to be expressed both on cancer epithelium and endothelium of adjacent stromal vessels, thus we decided to assess the correlation between EGFL7 and ICAM-1 matched according to the source of origin." (PMID 35630004, 2022). "Several studies have reported aberrant expression of EGFL7 and miR-126 in various human cancers, suggesting that EGFL7 and miR-126 play a joint role in cancer development." (PMID 35494025, 2022). "We expected to detect EGFL7 mRNA at least in endothelial cells as these reflect upregulation of EGFL7 gene in activated cancer vessels due to neoangiogenesis and/or inflammatory process." (PMID 35630004, 2022). "This provides direct information that in some parts, immune escape is achieved by limiting the influx of immune effectors into cancer tissue by activation of EGFL7." (PMID 35630004, 2022). "Further, we compared the number of (IE)CD4+ and (IE)CD8+ infiltrates between tumors with different EGFL7-status of cancer epithelium and endothelium." (PMID 35630004, 2022). "The ECM molecule EGFL7 is a critical player in the metastatic program, an inhibitor of the anti-cancer immune response escape, and contributes to drug resistance." (PMID 33804387, 2021). "This phenomenon is in agreement with previous studies reporting the methylation status of the corresponding CpG island localized in the human EGFL-7 gene in different cancer cell types." (PMID 34205549, 2021).
cancer (continued). "More importantly, Egfl7 has already been evidenced to be upregulated in the serum of patients with HCC or other type of cancers, suggesting its possible application in the diagnosis of HCC." (PMID 34217251, 2021). "We then further assessed the association between the expression of EGFL members and patient’s overall survival in 33 cancer types and found that the results varied in different cancer types, but EGFL6 and EGFL7 were mainly associated with poor prognosis." (PMID 33391349, 2020). "The results showed that the expression of EGFL8 was lower than EGFL6 and EGFL7 among all cancer types, wherein EGFL7 had the highest expression." (PMID 33391349, 2020). "EGFL6 had the highest correlation with the stromal score among all cancer types (r = 0.71, P < 0.001), following with EGFL7 (r = 0.65, P < 0.001) and EGFL8 (r = 0.19, P < 0.001)." (PMID 33391349, 2020). "EGFL7 was also showed to inhibit Notch signaling, which is a known key regulator in both cancer development and muscle stem cell activity, by a direct interaction with the Notch family of receptors." (PMID 32117731, 2020). "One candidate, Epidermal growth factor-like domain-containing protein 7 (EGFL7) has been proven to be a critical oncogene in various types of cancer." (PMID 31245291, 2019). "The correlation with prognosis is well in line with previous studies in locally advanced cancer as concerns miRNA-126, and with disseminated disease with respect to EGFL7." (PMID 35582589, 2019). "Our results are in line with the available literature regarding the critical role of EGFL7 in regulating cell migration and invasion of FBs, ECs and various cancer cells, thus influencing processes such as wound healing, vascular remodeling and metastasis." (PMID 30872612, 2019). "By RNA-seq, immunohistochemical staining (IHC), Western blot and luciferase reporter assay, we identified and confirmed EGFL7 as a direct functional target of miR-126 in cancer GCs." (PMID 31245291, 2019). "miR-126, harbored within the intron of the EGFL7 gene, is downregulated in cancer cell lines and also in primary bladder and prostate tumors." (PMID 30785618, 2018). "miR-126 and one of the transcripts of EGFL7 are concomitantly upregulated in cancer cell lines by inhibitors of DNA methylation and histone deacetylation." (PMID 30785618, 2018). "They demonstrated an elevated median EGFL7 concentration in serum from patients with different cancers, among these 64 patients with CRC, compared to a reference cohort of healthy donors." (PMID 28539619, 2017). "In human cancers elevated levels of EGFL7, assessed by immunohistochemistry (IHC) as well as qPCR, have been associated with increased risk of metastatic spread in several solid tumours." (PMID 25592646, 2015). "EGFL7 is a gene that has been found to play a role in cancer." (PMID 39869563, 2025). "Similarly, miR-126 and EGFL-7 levels were also lower in cancer tissues compared to paired normal tissues." (PMID 39796183, 2025). "A main involvement in the regulation of the miR-126-associated proliferation could be the epidermal growth factor-like domain-containing gene 7 (EGFL7) a master regulator of angiogenesis and cancer pathogenesis." (PMID 36733673, 2023). "Additionally, the RGD domain of EGFL7 is important to angiogenesis and EGFL7 has been linked to NOTCH and integrin signaling pathways besides cancers." (PMID 36309484, 2022). "Activation of EGFL7 in cancer cells and/or endothelial cells could negatively impact diapedesis regardless of localization." (PMID 35630004, 2022). "Endogenic EGFL7 activation in cancer cells and its upregulation in the endothelium are frequent in HGOSCs and could negatively impact diapedesis." (PMID 35630004, 2022). "One of the reasons for the discrepancy might be the different types of cancer, as the lung is inherently a highly vascularized tissue and maintains high levels of EGFL7." (PMID 35494025, 2022).